GPX3 (glutathione peroxidase 3)
Diseases named in the same sentence as GPX3 in open-access papers (continued):
Sharing a sentence is not in itself a finding about the gene and the disease.
tumor (continued). "Results showed that four prognostic genes (ADH1B, ADH4, UGT1A1, and GPX3) exhibited significantly lower expression in tumor samples compared to normal samples." (PMID 41031088, 2025). "GPX3 has been identified as a tumor suppressor in multiple cancers, where epigenetic regulation of its mRNA expression through hypermethylation of CpG islands in the promoter region specifically reduces transcriptional efficiency in many mammalian cancers." (PMID 41463386, 2025). "Among stromal FOV, GPX3 is the most significant downregulated gene in IO-exposed tumor cells (FDR < 0.001), and AZU1 was found to be downregulated in regulatory T cells (FDR < 0.001) and fibroblasts (FDR < 0.001)." (PMID 39639369, 2024). "Our data suggest that GPX3 mediates the AMPK/mTOR signaling pathway by regulating the level of ROS in tumor cells and triggering an imbalance of oxidative stress in the organism." (PMID 38322113, 2024). "For example, the tumour cell expressed genes CD24, CLU, and SLPI35–37 and the infiltrating cell expressed genes GPNMB, MGP, GPX3, and MFAP438–41 have all been previously associated with poor prognosis and chemotherapy resistance in HGSOC." (PMID 38570491, 2024). "This article reviews current advances in GPX3 research within non-neoplastic diseases, offering insights into its functions and mechanisms." (PMID 38927092, 2024). "GPX3 functions as a tumor suppressor, modulating apoptosis and cell growth; its downregulation compromises cellular metabolism, favoring tumor survival." (PMID 39594421, 2024). "It was found in multiple tumor cell lines that hypermethylation of the GPX3 promoter CpG island resulted in downregulation or complete silencing of GPX3 expression." (PMID 38927092, 2024). "The decreased expression of GPX3 in tumor tissue correlates with increased tumor cell proliferation and invasion, and poor prognosis, positioning GPX3 as a potential diagnostic marker and therapeutic target for tumors." (PMID 38927092, 2024). "Extensive studies have documented the aberrant expression of GPX3 in patients with various cancers, highlighting its involvement in tumor cell proliferation, adhesion, migration and metastasis." (PMID 38927092, 2024). "Research into the immunomodulatory roles of lung epithelial cells by the same group further revealed that the expression of glutathione peroxidase 3 (GPX3) was significantly increased in tumor exosomes-educated alveolar type 2 (AT2) epithelial cells." (PMID 38802766, 2024). "In lung cancer cells, GPx3 acts as an inhibitor of the proliferation, migration, and invasion of tumor cells by suppressing ROS-mediated NF-κB signaling." (PMID 39125992, 2024). "Amongst the differentially expressed EMT genes from that study, we find overlap with PTPRK-regulated genes including TGFB1, COL6A1, GPX3 and KLK10, as well as genes encoding LSR and PKP2, both of which are hyperphosphorylated in PTPRK KO tumours." (PMID 38904097, 2024). "We examined the relationship between GPX3 and tumor progression in 38 pairs GC tissues and adjacent normal tissues collected." (PMID 37790850, 2023). "We first used the CCK-8 assay to compare the effect of GPX3 on the proliferation rate of tumor cells." (PMID 36845676, 2023). "CDK1, ECT2, EZH2, GJB2, GPR37, GPX2, and GPX8 mRNA expression was up-regulated in the tumor group (p < 0.001), whereas GPX3, HYAL1, and TLR4 mRNA expression was down-regulated in the tumor group (p < 0.001) compared with those in the normal group." (PMID 37689745, 2023). "GPX3 is down-regulated in various tumor tissues, and GPX3 expression level can be used as a marker for cancer diagnosis." (PMID 36845676, 2023). "The immune checkpoint in GC is also an important component of tumor immune escape, so we investigated GPX3's relationship to immune checkpoints in GC." (PMID 37790850, 2023). "miR-196a suppression suppressed NSCLC stem cell self-renewal capacity, stemness, tumor growth and tumorigenicity through enhancement of expression of GPX3." (PMID 36876051, 2023).
tumor (continued). "Our results suggested that GPX3 plays a complicated role in the tumor microenvironment, simultaneously promoting metastasis and chemotherapy resistance in human cancers." (PMID 36845676, 2023). "In this study, we explored the role of GPX3 in human tumor diagnosis, prognosis, and sensitivity to treatment and its relationship to the tumor microenvironment." (PMID 36845676, 2023). "Suppression of this miRNA has suppressed stem cell self-renewal capacity, tumor growth and tumorigenicity through enhancement of expression of GPX3." (PMID 36876051, 2023). "Immunoinfiltration scores were used to assess the relationship between GPX3 and the tumor immune microenvironment." (PMID 36845676, 2023). "Our study further revealed the mechanisms by which GPX3 promotes tumor metastasis, growth, and chemotherapy resistance." (PMID 36845676, 2023). "It has been verified that GPX3 is consistently underexpressed in various tumor tissues, primarily due to the methylation of the GPX3 gene, resulting in decreased GPX3 activity." (PMID 37790850, 2023). "Our results showed that GPX3 expression was significantly reduced in tumor tissues compared with normal tissues, including BRCA, COAD, HNSC, KIRC, KIRP, LUAD, PRAD, and STAD." (PMID 36845676, 2023). "The anti-tumor activity of GPX3 depends on its downregulation of the oxidant-regulated tumor-promoting signaling pathway." (PMID 35978348, 2022). "For instance, glutathione peroxidase 3 (GPx3) has been correlated with a higher degree of invasion and tumor stage after liver resection in HCC." (PMID 36078082, 2022). "The recent GPX3 review described its dichotomous role in different cancer types; it can act as either an oncogene or a tumor suppressor." (PMID 35148810, 2022). "In contrast to the other genes in the GPX family, the GPX3 gene had a low expression level in all types of tumors, while it was also observed to be associated with better immune-cell subtypes and negatively with tumor stemness; this gene might therefore be a novel cancer inhibitor." (PMID 33706760, 2021). "We can reasonably infer that the GPX3 gene mainly plays an inhibitory role in the process of tumor occurrence and development, while the TXNRD1 gene mainly plays a promoting role." (PMID 33706760, 2021). "Mechanistic studies have started to identify the tumor suppressive function of GPx3 in cancers where GPx3 is known to be downregulated." (PMID 32781581, 2020). "It is possible that Se and glutathione utilization by tumor tissues depletes systemic levels and influences plasma GPx3 protein translations and activity." (PMID 32781581, 2020). "Studies have shown that GPx3 silencing promotes tumor metastasis in human gastric and thyroid cancer." (PMID 33322741, 2020). "Further studies are warranted, to examine how GPx3 affects oxidant scavenging and redox signaling in the extracellular tumor microenvironment." (PMID 33255360, 2020). "This aligns some of the time course of alterations, with GPX3 content falling within one week of tumor development and ROS generation occurring at two weeks." (PMID 33105841, 2020). "Below we summarize the major findings from studies demonstrating both tumor suppressive and pro-tumorigenic properties of GPx3." (PMID 32781581, 2020). "It is unclear if these stress response pathways contribute to the regulation of GPx3 in tumor cells with observed increases in GPx3 expression." (PMID 32781581, 2020). "From this it is evident that GPx3 has a dichotomous role in different tumor types, acting as both a tumor suppressor and pro-survival protein." (PMID 32781581, 2020). "In papillary serous ovarian cancer systemic levels of GPx3 are decreased in a tumor-stage dependent manner, with late stage patients displaying a more pronounced decrease in plasma GPx3 levels." (PMID 32781581, 2020).
tumor (continued). "Recent reports suggest that GPx3 ablation enhances tumor inflammation, injury, proliferation, and DNA damage in mice subjected to inflammatory carcinogenesis and chronic colitis." (PMID 33322741, 2020). "In tumor cells, GPx3 is often a target of hypermethylation and its downregulation is associated with bad prognosis and chemoresistance in several types of tumor." (PMID 32426284, 2020). "We highlight studies focused on the role and regulation of GPx3 in cancer, at both the systemic level and in response to altered expression by tumor cells." (PMID 32781581, 2020). "Further studies are needed to explore the GPX3 promoter methylation pattern in AML patients and to understand the role of GPX3 as tumor suppressor gene and its relation with molecular cytogenetics involved in AML." (PMID 33369453, 2020). "CD177 and AQP8 were downregulated in all 79 CRCs while GPX3, a “tumor suppressor”, was downregulated in 75 out of 79 CRCs (log2T/N < 0)." (PMID 31409279, 2019). "The results revealed that overexpression of GPx3 efficiently suppressed proliferation, healing, and invasion of tumor cells, whereas knocking down GPx3 had the opposite effect." (PMID 30260967, 2018). "The putative mechanisms involved in mediating the GPX3 tumor-suppressing role are primarily attributed to promoter hyper-methylation, dysregulation of c-Met expressions, and the enzymic role of antioxidants that scavenge the detrimental free radicals." (PMID 30469536, 2018). "The most important cellular characteristic of GPx3 is its tumor suppressor activity, which has been reported by many groups." (PMID 30260967, 2018). "Even though the underlying molecular mechanisms are not yet sufficiently understood, these results indicate that GPX3 activity is tumor-specific." (PMID 30469536, 2018). "GPX3 was among an 8-gene signature panel that had been used for predicting the status (normal versus tumor) of gastric tissues with an accuracy of >96%." (PMID 30143675, 2018). "First, to examine the antioxidant effects of GPx3 on tumor suppression, we used cells subjected to oxidative stress via serum starvation (to induce production of endogenous H2O2) rather than exposure to exogenous oxidants." (PMID 30260967, 2018). "Downregulation of GPx3 via promoter hypermethylation occurs in many types of human cancer, suggesting that GPx3 acts as a tumor suppressor." (PMID 30260967, 2018). "Among these, IGJ (immunoglobulin J chain, linker protein for immunoglobulin alpha and mu) was previously reported as having a significant difference of expression in HCC tumors, while GPX3 (glutathione peroxidase 3) was reported as a tumor suppressor in HCC." (PMID 30598095, 2018). "We investigated mRNA expression of GPX3 in 76 paired ccRCC tumor tissues and their adjacent non-tumor tissues using quantitative Real-Time PCR." (PMID 25970749, 2015). "Of note, we observed promoter hypermethylation and downregulation of GPX3 in a small number of tumor-adjacent “normal” renal tissues." (PMID 25970749, 2015). "In adjacent non-tumor tissues, intense immunostaining for GPX3 was observed in a cytoplasmic distribution, whereas absent/weak immunostaining was detected in the cytoplasm of tumor tissues." (PMID 25970749, 2015). "GPX3 was significantly downregulated in renal tumors compared with their adjacent non-tumor tissues (p < 0.0001)." (PMID 25970749, 2015). "Consistent with mRNA levels, the protein levels of GPx3 were also found down-regulated in tumor tissues." (PMID 25333265, 2014). "The down-regulation of GPx3 within tumor tissue also significantly correlated with advanced tumor stage and appearance of venous infiltration in HCC patients." (PMID 25333265, 2014). "The tumor suppressive role of GPx3 was studied by administration of recombinant GPx3 (rGPx3) or over-expression of GPx3 in HCC cells in vitro and in vivo." (PMID 25333265, 2014).
tumor (continued). "We demonstrated that the lower plasma GPx3 indicated tumor recurrence and shorter disease-free-survival period of HCC patients after liver resection." (PMID 25333265, 2014). "The co-localization of hiPSC-MSCs and GPx3 expressions detected within tumor tissues highly implied that GPx3 can be successfully delivered by hiPSC-MSCs into the tumor site." (PMID 25333265, 2014). "More importantly, we demonstrated, for the first time that the tumor suppressive activity of GPx3 delivered by hiPSC-MSCs indicated the therapeutic potential of hiPSC-MSC-GPx3 for HCC patients." (PMID 25333265, 2014). "It has also been noticed that expression of GPx3 is significantly down-regulated within tumor tissues in several types of cancers." (PMID 25333265, 2014). "Much lower expression levels of GPx3 were observed in colorectal cancer compared with non-tumor tissues." (PMID 25333265, 2014). "Fourthly, we found that the tumor suppressive activity of GPx3 was mediated by inhibition of EMT (Epithelial-Mesenchymal Transition) through Erk-NFκB-SIP1 signaling pathway." (PMID 25333265, 2014). "We not only investigated the clinical significance, but also further demonstrated the tumor suppressive role of GPx3 in HCC in vitro and in vivo." (PMID 25333265, 2014). "The larger tumor size (P = 0.011) and higher number of tumor nodules (P = 0.032) were found in the GPx3 low level group." (PMID 25333265, 2014). "Epigenetic hypermethylation and genome deletion are reported as two reasons for the down-regulation of GPx3 during cancer development, but the mechanism of down-regulation of GPx3 contributing to tumor progression remains to be investigated." (PMID 25333265, 2014). "The down-regulation of GPx3 in tumor tissues compared with adjacent non-tumor tissues was observed in 50% of HCC patients (56/113)." (PMID 25333265, 2014). "The over-expression of GPx3 in MHCC97L-GPx3-2 group was also confirmed 5 weeks after tumor implantation." (PMID 25333265, 2014). "The average mRNA level of GPx3 was significantly lower within tumor tissues compared with adjacent non-tumor tissues and normal liver tissues." (PMID 25333265, 2014). "Lower plasma GPx3 in HCC patients was significantly associated with larger tumor size (P = 0.011), more tumor nodules (P = 0.032) and higher recurrence (P = 0.016)." (PMID 25333265, 2014). "Expression levels of selenoproteins including Gpx-1, Gpx-3, and Sepp1 are significantly decreased in colorectal cancer, with lowered Sepp1 expression correlating most significantly with tumor stage." (PMID 23861820, 2013). "Based on our analysis of gene PARTP, GPX1, GPX3, and SELS were associated with ER-/PR+ tumor status, while SELS was also associated with ER+/PR- tumors." (PMID 24278290, 2013). "Quantitative analysis of GPX3 promoter DNA methylation, indicated increased promoter DNA methylation levels of all tested CpG nucleotides in tumor samples compared with normal samples." (PMID 23071548, 2012). "We also observed downregulation, DNA copy number losses, and promoter hypermethylation of GPX3 in approximately one-third of tumor-adjacent normal gastric tissue samples, suggesting the presence of a field defect in areas near tumor samples." (PMID 23071548, 2012). "Further analysis of 24 paired tumor and normal samples confirmed the significant downregulation of GPX3 mRNA expression in tumors as compared with their corresponding normal samples." (PMID 23071548, 2012). "The comparison of GPX3 copy number in 22 matched tumor and normal samples demonstrated lower levels of DNA copy numbers in tumors (P = 0.058)." (PMID 23071548, 2012). "Their findings also suggest that the GPX3 tumor suppressor activity seems to involve transcriptional regulation of the tumor oncogene, MET." (PMID 21106063, 2010). "GC tissues show GPX3 downregulation, which increases oxidative stress and tumor development." (PMID 41031088, 2025).
tumor (continued). "This suggests that TIAM1 may function as an oncogene, while RAP1GAP, JUN, and GPX3 might act as tumor suppressors." (PMID 40092686, 2025). "In addition, studies utilizing GPx3 KO mice have shown accelerated dysplasia in tumor lesions and an increased incidence of cancer." (PMID 38732573, 2024). "GPx3 expression was lower in tumor tissues compared to normal tissues." (PMID 38732573, 2024). "Some results suggest that GPx3 plays a complicated role in the tumor microenvironment, simultaneously promoting metastasis and chemotherapy resistance in human cancers due to enhancing the removal of H2O2 and lipid hydroperoxides from the extracellular tumor environment." (PMID 39125992, 2024). "In this study, GPX3 was identified as a key target for regulating ROS in tumor cells, whose expression is downregulated in STAD and this could affect the prognosis of patients with this disease." (PMID 38322113, 2024). "Moreover, the expression of GDI1 was up-regulated in tumor samples, whereas GPX3 and SLC39A8 were down-regulated in tumor samples." (PMID 39006076, 2024). "The results showed lower GPx3 expression in tumor tissues compared to normal tissues." (PMID 38732573, 2024). "In melanoma, the upregulation of GPx3 plays a role in regulating ROS levels by inhibiting the expression of HIF1α, which is upregulated in various human cancers and plays a key role in driving tumor growth, invasion, and metastasis." (PMID 39125992, 2024). "Thus, in relevant experimental studies, GPX3 sometimes exerts opposite effects on tumor cells due to different intracellular ROS concentrations." (PMID 38322113, 2024). "However, the significance of GPX3 in non-neoplastic diseases also merits attention, as emerging research underscores its pivotal role in these conditions." (PMID 38927092, 2024). "To test this hypothesis, we simultaneously analysed three complementary biomarkers of Se status (total serum Se, SELENOP, GPx3) and conducted bulk RNA-sequencing of tumours of 1453 patients with a new diagnosis of primary invasive breast cancer." (PMID 37741974, 2023). "Subsequently, we hoped to explore the relationship between GPX3 expression and tumor metastasis." (PMID 36845676, 2023). "The results showed that CALB2 and GPX3 were highly expressed in most tumor tissues." (PMID 37664836, 2023). "We explored the effect of GPX3 on ROS production in tumor cells." (PMID 36845676, 2023). "Additionally, our research found a link between elevated GPX3 expression and more advanced clinical indicators, suggesting a potential function for GPX3 in tumor progression." (PMID 38042786, 2023). "In addition to an increase in inflammation levels, the number of tumor cells also increased in the number of tumor cells after GPX3 KO during the development of colitis-related cancers." (PMID 36937839, 2023). "GPX3 functions as a tumor suppressor, and its downregulation is widely observed in PCa." (PMID 38139289, 2023). "Moreover, our finding is in line with several studies confirming a lower expression of GPX3 in the tumor tissue." (PMID 37629712, 2023). "Nevertheless, it was plausible that GPX3 may also facilitate tumor progression to advanced stages by promoting immune cell infiltration and activating immune checkpoints." (PMID 37790850, 2023). "To further resolve the pathways potentially regulated by CALB2 and GPX3 in the TCGA dataset, we compared the pathways with significantly enriched pathways in tumor tissues and paraneoplastic tissues by GSVA method and calculated the GSVA scores of all pathways." (PMID 37664836, 2023). "Studies have reported the relationship between the downregulation of GPX3 and tumor metastasis." (PMID 36845676, 2023). "In addition to an increase in inflammation levels, the number of tumor cells also increased during the development of colitis-related cancers in gpx3 knockouts." (PMID 37761814, 2023). "Furthermore, we explored the relationship between GPX3 and immune invasion in the tumor microenvironment (TME)." (PMID 36845676, 2023).